MTOR (mechanistic target of rapamycin kinase)
Diseases named in the same sentence as MTOR in open-access papers (continued):
Sharing a sentence is not in itself a finding about the gene and the disease.
MTOR also shares sentences with these, for which no sentence is quoted: hypertrophy (20 papers); renal tumors (15); Parkinson’s (14); Alpha-thalassemia (7); acute myocardial infarction (6); myelodysplastic syndrome (6); Chagas disease (5); Lafora disease (5); large cell carcinoma (5); neurotoxicity (5); Skeletal muscle atrophy (5); arrhythmogenic right ventricular cardiomyopathy (4); channelopathies (4); cutaneous T cell lymphoma (4); digestive system cancer (4); Glomerular sclerosis (4); oncocytic tumor (4); portal hypertension (4); Sjögren's Syndrome (4); uterine cancer (4); Abdominal obesity (3); aphthous ulcers (3); Bannayan-Riley-Ruvalcaba syndrome (3); celiac disease (3); choroidal melanoma (3); chronic hepatitis (3); chronic prostatitis (3); cognitive disorder (3); dental fluorosis (3); Encephalopathy (3).
A further 418 diseases each share a sentence with MTOR in 3 papers or fewer.